NES (nestin)
Diseases named in the same sentence as NES in open-access papers (continued):
Sharing a sentence is not in itself a finding about the gene and the disease.
Obesity (12 papers, 2008 to 2025). Accumulation of substantial excess body fat. "We generated mice with conditional deletion of PI3Kγ in neurons using the nestin promoter to drive the expression of the Cre recombinase (PI3KγNest mice) and investigated their metabolic phenotype in a model of diet-induced obesity." (PMID 39811649, 2025). "Nestin-CRE mice showed significant protection from diet-induced obesity compared to littermate WT mice." (PMID 39811649, 2025). "Here, we showed that knockdown of Lgr4 in nestin progenitor or Sp1 mature neurons reduced high fat diet (HFD)-induced obesity by increasing energy expenditure and inhibiting food intake." (PMID 40069508, 2025). "We found that deletion of Lepr specifically in nestin-expressing cells led to extreme obesity, but the conditional null of Lepr in Shh-expressing cells had no obvious phenotype." (PMID 32746867, 2020). "This study shows the possibility of using psoriasin, nestin, Krt16, and IL-21 as biochemical markers of psoriasis and highlights the correlation of these with biomarkers of obesity (BMI, leptin, and resistin)." (PMID 31275060, 2019). "The objective was to establish if psoriasin, nestin, Krt16, and IL-21 were possible biomarkers of psoriasis and to correlate them with Body Mass Index (BMI), leptin, and resistin (biomarkers of obesity)." (PMID 31275060, 2019). "However, the weight gain of Nestin-Cre mice was similar to the one of PI3KγF/F mice, and PI3KγNest mice showed marked protection from diet-induced obesity compared to all the control groups, including Nestin-CRE mice." (PMID 39811649, 2025). "Here, we find that deletion of PC1/3 in obesity-related neuronal cells expressing proopiomelanocortin mildly and transiently change body weight and fail to produce a phenotype when targeted to Agouti-related peptide- or nestin-expressing tissues." (PMID 35963866, 2022). "HCD-depletion of the Common Lymphoid Progenitor (CLP) and B cell-differentiation-promoting CXCL12 abundant reticular (CAR) cells in the BM additionally reinforces the myeloid/lymphoid bias as does the HCD enhancement of Nestin+ MSCs, which drive the adipocyte bias of the BM niche in obesity." (PMID 36105811, 2022). "An even stronger decrease in cardiac UCP3 content was observed in the LoxTB MC4R−/− mice (28–34% decrease) and LepR/Nestin-cre mice (38–40% decrease), two other models of type 2 diabetes which are also characterized by severe obesity, insulin resistance, hyperinsulinemia, and glucose intolerance." (PMID 30374710, 2018). "In both crosses, the homozygous LSL-PrRP littermates show divergent body weights at 8 to 9 weeks of age on normal chow when compared with the wild-type and the Cre-expressing mice; however, the obesity is fully reversed in the nestin-Cre::LSL-PrRP and TH-Cre::LSL-PrRP mice." (PMID 25176149, 2014). "Thus, similar to many other mouse models of obesity, Stat5fl/fl; Nestin-Cre mice demonstrated some features of metabolic syndrome, including hyperlipidemia, hyperinsulinemia, insulin resistance and glucose intolerance." (PMID 18286195, 2008). "Since STAT5 signaling is central to GM-CSF action, we hypothesized that diminished GM-CSF action in the CNS may contribute to the obesity of Stat5fl/fl; Nestin-Cre animals." (PMID 18286195, 2008). "Since reduced SOCS3 expression in the Arc would tend to increase signaling by leptin and other cytokines to promote leanness, the regulation of hypothalamic SOCS3 expression by STAT5 is also unlikely to underlie the obesity of the Stat5fl/fl; Nestin-Cre mice." (PMID 18286195, 2008). "Diet-induced obesity increases hypothalamic JNK activity and germ-line deletion of JNK1 from nestin expressing cells results in protection from diet-induced glucose intolerance and insulin resistance." (PMID 31765625, 2020). "AP treatment was sufficient to induce partial recovery of obesity-related stem cell depletion and to replenish CD133+ and Nestin+ cell abundance." (PMID 30612898, 2019).
Obesity (continued). "Here, we utilize 3D human cerebral organoids and 2D neural progenitor cells derived from human embryonic stem cells harboring WFS1 deficiency and Wfs1 conditional knockout mice (Wfs1flox/flox X Nestin‐Cre, CKO) exposed to HFD to examine the vicious cycle of obesity and depression." (PMID 39258564, 2024).
malignant glioma (11 papers, 2006 to 2021). A grade III or grade IV glioma arising from the central nervous system. "Co-expression of CD133 and nestin is associated with a poor prognosis for malignant glioma patients." (PMID 24732116, 2014). "On average, 15% (range 2–19%) of malignant glioma cells expressed IL-17R and more than 60% of IL-17R+ cells co-expressed the GSC markers CD133, Nestin, and Sox2." (PMID 26755664, 2016). "Of note, in S24 GIC treatment with DZNep led to a downregulation of the stem cell marker nestin, which is in line with previous reports showing that EZH2 is crucial for maintaining a stem cell phenotype in malignant glioma." (PMID 23077658, 2012). "In contrast, an incomplete co-localization of nestin with intermediate filament bundles containing other intermediate filament proteins (vimentin, GFAP, neurofilament) has been detected in the cell lines derived from PNETs and malignant gliomas." (PMID 16457706, 2006). "Furthermore, EZH2 is also a known regulator of Nestin expression in malignant gliomas, which we found to be decreased in PN but not MES GICs after FTH1 knockdown in our study." (PMID 31491006, 2019).
colorectal cancer (10 papers, 2014 to 2025). A primary or metastatic malignant neoplasm that affects the colon or rectum. "Nestin has been particularly reported as an efficient marker to detect the presence of newly formed micrangium in colorectal cancer." (PMID 26762567, 2016).
meningioma (10 papers, 2012 to 2026). A generally slow growing tumor attached to the dura mater. "The high expression of AGR2 has been previously associated with the expression of Nestin, CD133 and SOX2 in high-grade meningioma tissues." (PMID 36482387, 2022). "On the contrary, expression of Nestin and hTERT varied across cell lines, although both showed significantly strong expression in the transitional meningioma cell line M3." (PMID 32742192, 2020). "The expression of Nestin and hTERT has been reported to be closely correlated to progression and recurrence in meningioma." (PMID 32742192, 2020). "Perhaps in meningioma, Nestin overexpression occurs as an early event in the process of CSCs generation." (PMID 28736504, 2017). "Interestingly, it also showed a significantly higher mRNA expression level of Nestin compared with all the meningioma cell lines." (PMID 32742192, 2020). "Unexpectedly, the expression level of Nestin and hTERT in atypical meningioma cells was not higher than what was observed in the other benign meningioma cells." (PMID 32742192, 2020). "Higher expression of Nestin has been detected in grades II and III meningiomas compared to grade I." (PMID 29849507, 2018). "The fraction of Ki67+ cells that were Nestin negative were more frequent in grade II/III meningiomas, even though Nestin expression tended to slightly increase with grade." (PMID 29849507, 2018). "Meningioma tissues and primary cell lines were investigated using whole transcriptome microarray analysis, immunofluorescence staining of CSCs markers (including CD133, Sox2, Nestin, and Frizzled 9), and drug treatment with cisplatin or etoposide." (PMID 28736504, 2017). "Regions that were significantly frequently occurring in grade II/III but never in grade I meningiomas included those that were positive for CD133+SOX2±Vimentin+FZD9+GFAP+BTIII+SSEA4+Olig2+, and Nestin+Ki67+CD133+Vimentin+FZD9+GFAP+BTIII+SSEA4+Olig2+." (PMID 29849507, 2018). "Meningioma cells exhibited immunoreactivity for CD133, and a lack of immunoreactivity for nestin (data not shown)." (PMID 22754374, 2012).
myeloproliferative neoplasm (9 papers, 2015 to 2023). A clonal hematopoietic stem cell disorder, characterized by proliferation in the bone marrow of one or more of the myeloid (i.e., granulocytic, erythroid, megakaryocytic, and mast cell) lineages. "Pharmacological treatment with β3-adrenergic agonists reduced Nestin+ MSCs loss and disrupted myeloproliferative neoplasm evolution." (PMID 34869355, 2021). "In preclinical models of myeloproliferative neoplasms, a subclass of hematological cancer, our recent work has provided evidence on the pathogenic role of bone marrow Nestin+ cell alterations, and the promising therapeutic value of their targeting." (PMID 29541793, 2018). "Sympathoadrenergic fibers, supporting Schwann cells and nestin(+) mesenchymal stem cells are reduced in the BM of patients with myeloproliferative neoplasms as well as in mice expressing the human JAK2(V617F) mutation in HSCs." (PMID 26300737, 2015). "In myeloproliferative neoplasms, the Schwann cells and Nestin+ MSCs are reduced due to neural damage of the bone marrow mediated by IL-1β, produced by malignant cells, which resulted in an expansion of deffective mesenchymal stem and progenitor cells." (PMID 34869355, 2021). "Nestin+ niches are reduced in humans or mice with chronic myeloproliferative neoplasms, which can be considered preleukemic disorders due to their higher incidence of leukemic transformation." (PMID 32966766, 2020). "Nestin+ cell number and Nestin messenger RNA expression are also reduced in the bone marrow of patients with myeloproliferative neoplasms." (PMID 29541793, 2018). "Treatment with β3-AR agonists restore the sympathetic regulation of nestin(+) mesenchymal stem cells, blocking myeloproliferative neoplasms progression by indirectly reducing the number of leukaemic stem cells." (PMID 26300737, 2015). "Patients with myeloproliferative neoplasms have reduced sympathetic nerve fibres, supporting Schwann cells and Nestin+ MSCs in the bone marrow, mainly due to bone marrow neural damage by interleukin-1β, which is produced by mutant HSCs and favours their expansion." (PMID 32048054, 2020). "Nonetheless, our data suggest that targeting the beta-3 adrenergic receptor with agonist drugs may have clinical implications to improve treatment of patients with myeloproliferative neoplasms, and Nestin+ cells contribute to these events." (PMID 29541793, 2018). "Also, myeloproliferative neoplasms (MPN) patients show fewer sympathetic nerve fibers in the BM that support Schwann cells and Nestin+ MSCs." (PMID 37735675, 2023).
myocardial infarction (9 papers, 2013 to 2025). Gross necrosis of the myocardium, as a result of interruption of the blood supply to the area, as in coronary thrombosis. "On the contrary, angiogenesis is activated after the myocardial infarction that results in appearance of nestin positivity in the endothelial cells of the blood vessels growing in the border zone." (PMID 36690826, 2024). "In our previous work, we detected nestin in human myocardium of patients who died after myocardial infarction." (PMID 36690826, 2024). "Not only in mesenchymal stromal cells, but also in bone-derived mesenchymal stem cells, Nestin has been shown to positively regulate cardiac function in an acute myocardial infarction mouse model." (PMID 32635662, 2020). "The impact of a type I diabetic environment on the neurogenic response of cardiac nestin(+) cells was examined during myocardial infarction and following the administration of 6-hydroxydopamine." (PMID 23938193, 2013). "Nestin works as an active marker of tumor angiogenesis in the digestive tract and damaged myocardium in myocardial infarction (MI) model rats." (PMID 37735673, 2023). "In the normal adult rodent heart, neural crest-derived nestin(+)-neural progenitor/stem cells are intercalated between cardiomyocytes and following myocardial infarction (MI) migrate to the scar region." (PMID 29492403, 2018). "It has been reported that vascular SMCs express nestin, but nestin expression has also been described in endothelial cells, e.g. in proliferating endothelial progenitor cells, as precursors of endothelial cells in the lymph node and in developing vessels after myocardial infarction." (PMID 29874225, 2018). "The appearance of nestin(+)-ventricular cardiomyocytes post-myocardial infarction (MI) recapitulates an embryonic phenotype and depletion of the intermediate filament protein inhibits cell cycle re-entry." (PMID 29492403, 2018). "After transplantation into mice exposed to myocardial infarction (MI), Nestin+ BMSC-treated mice showed significantly improved survival and left ventricular function compared with Nestin− BMSC-treated mice." (PMID 31029167, 2019).
sarcoma (9 papers, 2020 to 2025). A usually aggressive malignant neoplasm of the soft tissue or bone. "The LMNA-NTRK1 fusion-positive sarcoma revealed CD34/S100 protein/nestin/CD10 coexpression, and a low mitotic rate." (PMID 32957984, 2020). "Nestin has been shown to be expressed in different cells and tissues and in many types of cancer, including in specific sarcoma subtypes, such as RMS and malignant peripheral nerve sheath tumor (MPNST)." (PMID 32532153, 2020). "Also, the TPR-NTRK1 fusion-positive sarcoma showed robust positivity for CD34/nestin, and also showed high mitotic rate." (PMID 32957984, 2020). "Analysis of stemness markers showed genes NES, POUF1, and SOX2 all have a greater expression in CSC than in the parental cell lines of sarcomas, with SOX2 being significantly more expressed in the CSC cell line." (PMID 41300532, 2025). "Our work showed that EMX1/EMX2 act as tumor suppressors in sarcomas by repressing the activity of stem cell regulatory genes (OCT4, SOX2, KLF4, MYC, NANOG, NES, and PROM1)." (PMID 34016958, 2021). "In summary, our work showed that EMX1 and EMX2 act as tumor suppressors by suppressing the activity of stem cell regulatory genes (OCT4, KLF4, MYC, SOX2, NANOG, NES, and PROM1) in sarcoma." (PMID 34016958, 2021). "A reduction in the expression of NESTIN (NES) was also observed in the EMX-positive cell population, reaffirming the markers NES and CD133 as markers enriched in stem cells in sarcoma and regulated by the expression of EMX." (PMID 34016958, 2021). "Co-expression of nestin, CD133 and ABCG2 as putative CSC markers has been studied in different type of sarcomas." (PMID 31983166, 2020). "In murine knockout (KO) models lacking Emx genes, 3MC-induced sarcomas were more aggressive and infiltrative, had a greater capacity for tumor self-renewal, and had higher stem cell gene expression and nestin expression than those in wild-type models." (PMID 34016958, 2021). "On the other hand, high expression of nestin has been correlated with poor prognosis in EWS, suggesting that this protein may also be a prognostic factor in sarcomas." (PMID 32532153, 2020). "Similar results were reported in pediatric sarcomas, where high expression of CD133 and nestin, but not of ABCG2, were associated with shorter survival in RMS and EWS patients, supporting the potential prognostic value of CD133 in sarcomas." (PMID 32532153, 2020). "Although the first studies suggested prominin-1 (CD133) or nestin as rhabdomyosarcoma CSC markers, our recent study showed that, regardless of these proteins, only sarcoma cell lines that express high levels of the transcription factor SOX2 form tumors in immunodeficient NOD/SCID gamma (NSG) mice." (PMID 31941033, 2020). "The TPR-NTRK1 fusion sarcoma was positive for CD34 and nestin but negative for S100 protein." (PMID 32957984, 2020).
colon carcinoma (8 papers, 2010 to 2024). "Immunocytochemical analysis of CD133, CD44 and Nestin expression of colon adenocarcinoma cell line HT-29 and colon carcinoma cell line HCT-116 only revealed slight expression of these CSC-markers." (PMID 32927768, 2020). "The colon cancer derived tumour spheres obtained in this study were evaluated for expression of a panel of stem cell markers, including BMI-1, nestin (NES), and musashi-1 (MSI-1)." (PMID 20332776, 2010). "Using a colon cancer cell line HCT-116 and primary colon cancer cells, we have found that IL-1β can promote sphere-forming capacity concomitant with up-regulated expression of stemness markers Bmi1 and nestin in colon cancer cells, suggesting that IL-1β increases the self-renewal of colon CSCs." (PMID 23174018, 2012). "IL-1β may foster CRC growth and invasion by stimulating colon cancer stem cell (CSC) self-renewal and upregulating stemness factor genes Bmi1 and Nestin." (PMID 38671854, 2024). "To date, the experimental data to support Oct-4 and Nestin as colon cancer stem cell markers are still lacking." (PMID 21694723, 2011).
ependymoma (8 papers, 2007 to 2024). A WHO grade II, slow growing tumor of children and young adults, usually located intraventricularly. "By charting the time-evolved expansion of Nestin+/Ki67+ cells as well as their spatial location, our in vitro models provided a platform for examining the abnormal transformation and progression of ependymoma-associated stem/progenitor cells." (PMID 37508868, 2023). "Previous studies have demonstrated increased expression of stem cell marker nestin to be associated with poor prognosis in intracranial ependymomas, with high expression levels in RELA fusion positive ST EPNs." (PMID 30464804, 2018). "Our finding of VEGF-associated Nestin+ cell enrichment suggested that VEGF could augment cancer stem cell survival in ependymoma." (PMID 37508868, 2023). "In ependymoma, nestin expression is associated with aggressive grade 2 tumors." (PMID 35204045, 2022). "Nestin+ cells appeared to form the tumor stem cell niche that predominated ependymoma’s in vitro growth." (PMID 37508868, 2023). "While it has been reported that VEGF expression has no strong association with aberrant vascular patterns or angiogenic activity, other studies observed the significant co-expression of VEGF and Nestin in ependymomas of different grades and locations." (PMID 37508868, 2023). "Nestin, an intermediate filament characteristic of neural progenitors, is commonly found in ependymoma; however, the identity of the cell of origin of ependymoma is still unclear." (PMID 37508868, 2023). "Our in vitro ependymoma cultures demonstrated, for the first time, Nestin+ cell replication in the tumor growth niche, thus suggesting its role as the cancer stem cell of ependymoma." (PMID 37508868, 2023). "Among the cell types we tested, the Nestin+ population showed the strongest correlation with media differences of ependymoma cultures." (PMID 37508868, 2023). "Though cyclin D1, nestin, and Ki-67 are well-studied in ependymoma, data from additional cohorts are needed." (PMID 35204045, 2022). "We investigated the immunohistochemical expression of p27 and p57 in ependymoma, with a secondary emphasis on cyclin D1, nestin, and Ki-67." (PMID 35204045, 2022). "Cyclin D1, nestin, and Ki-67 are useful markers in ependymoma, but evidence-based cutoff values are required to standardize interpretation." (PMID 35204045, 2022). "We investigated the immunohistochemical expression of p27 and p57 in 65 cases of ependymoma, with a secondary emphasis on cyclin D1, nestin, and Ki-67." (PMID 35204045, 2022). "Cyclin D1, nestin, and Ki-67 are useful markers in ependymoma, but evidence-based cutoff values are required to standardize this interpretation." (PMID 35204045, 2022). "A recent publication showed that YAP1-MAMLD1 fusion in nestin-positive neural stem cells induce ependymoma-like tumours in mice." (PMID 32404936, 2020). "These constructs were then tested in Nestin-Cre+/−;Cag-Cas9+/+ mice to target Nestin+ radial glia, the putative cell of origin for ependymomas." (PMID 33228790, 2020). "Other established markers of poor prognosis in ependymoma include nestin and Ki-67." (PMID 35204045, 2022). "Therefore, we investigated the immunohistochemical expression of p27 and p57 in ependymoma, with a secondary emphasis on the expression of cyclin D1, nestin, and Ki-67." (PMID 35204045, 2022).